LIPT1 (lipoyltransferase 1)
Description:
Lipoyl amidotransferase that catalyzes the transfer of lipoyl moieties from lipoyl-protein H of the glycine cleavage system (lipoyl-GCSH) to E2 subunits of the pyruvate dehydrogenase complex (PDCE2). Unable to catalyze the transfer of octanoyl from octanoyl-GCSH to PDCE2. In vitro, it is also able to catalyze the transfer of the lipoyl group from lipoyl-AMP to the specific lysine residue of lipoyl domains of lipoate-dependent enzymes but this reaction may not be physiologically relevant (Probable).
Synonyms: MGC12290; MGC13378; LIPT1D
Tractability: PROTAC: ubiquitination databases record sites on it.
Gene: Protein-coding gene on chromosome 2 (99,154,955 to 99,163,179, forward strand). Ensembl gene ENSG00000144182.
Subcellular location: Mitochondrion
Pathways (Reactome):
Metabolism of proteins: Protein lipoylation
Gene Ontology:
Molecular function: protein binding; acyltransferase activity, transferring groups other than amino-acyl groups; lipoyltransferase activity
Biological process: lipid metabolic process; protein lipoylation; protein modification process
Cellular component: mitochondrion; cytoplasm; mitochondrial matrix
Genetic constraint (gnomAD): Loss-of-function variants: 22 observed, 26.45 expected, observed/expected ratio (o/e) 0.83, 90% interval 0.59 to 1.19. The upper end of that interval is the gene's LOEUF score, 1.19, which puts it in group 5 of 6, group 1 being the genes least tolerant of losing a copy. Missense variants: 399 observed, 453.7 expected, observed/expected ratio (o/e) 0.88, 90% interval 0.81 to 0.95. Synonymous variants: 131 observed, 160.34 expected, observed/expected ratio (o/e) 0.82, 90% interval 0.71 to 0.94.
Gene-disease validity (ClinGen):
ClinGen rates the evidence that LIPT1 causes each of these diseases.
Leigh syndrome (autosomal recessive): Moderate. A progressive neurological disease defined by specific neuropathological features associating brainstem and basal ganglia lesions.
Homologues: Orthologues: chimpanzee LIPT1 (99% identical), dog LIPT1 (90% identical), rabbit LIPT1 (88% identical), mouse Lipt1 (81% identical), rat Lipt1 (81% identical), tropical clawed frog lipt1 (60% identical), guinea pig LIPT1 (54% identical), zebrafish lipt1 (52% identical), Drosophila melanogaster Lipt1 (32% identical), Caenorhabditis elegans lipt-1 (30% identical).
Diseases named in the same sentence as LIPT1 in open-access papers:
LIPT1 is named in the same sentence as 102 diseases in open-access papers, as found by Europe PMC text mining. Sharing a sentence is not in itself a finding about the gene and the disease. The quoted sentences say what the papers report.
melanoma (19 papers, 2022 to 2025). A malignant, usually aggressive tumor composed of atypical, neoplastic melanocytes. "Studies have shown that LIPT1 is closely linked to a favorable outcome in patients with urothelial cancer, hepatocellular carcinoma, and melanoma." (PMID 36911392, 2023). "Even though LIPT1 has been proved to be upregulated in melanoma, the detailed roles and underlying mechanisms of LIPT1 in human cancers are unclear and warrant further exploration." (PMID 36330439, 2022). "Additionally, the expression of the LIPT1 gene has been linked to PD-L1 expression, regulatory T-cell infiltration, and longer survival in melanoma patients who were treated with immunotherapy." (PMID 38336727, 2024). "Some studies have shown that LIPT1 plays an oncogenic role in patients with uroepithelial carcinoma or melanoma, but others have found that LIPT1 expression is up-regulated in LIHC, which is an independent prognostic factor for the poor prognosis of LIHC." (PMID 40367233, 2025). "Among these genes, LIPT1 has emerged as a advantageous prognostic marker for individuals with melanoma." (PMID 38336727, 2024). "An analysis of CRGs demonstrated the prognostic value of these genes, especially LIPT1, in melanoma and the correlation between LIPT1 expression with immune infiltration." (PMID 38970072, 2024). "Further exploration found that LIPT1 expression was increased in melanoma biopsies and was an independent favorable prognostic indicator for melanoma patients." (PMID 37035162, 2023). "LIPT1 expression is elevated in melanoma biopsies, and is an independent favorable prognostic indicator in melanoma patients." (PMID 36843949, 2023). "In the survival analysis of the 19 cuproptosis-related genes in melanoma patients, seventeen cuproptosis-related genes have significant differences, while LIPT1 and NLRP3 showed the most significant differences." (PMID 37138850, 2023). "They discovered that 11 out of 12 genes were upregulated in melanoma tissues and that three genes (LIPT1, PDHA1, and SLC31A1) have predictive value for the prognosis." (PMID 36454396, 2022). "LIPT1 expression was increased in melanoma biopsies and was an independent favorable prognostic indicator for melanoma patients." (PMID 35837286, 2022). "The multivariate analysis indicated that LIPT1 expression was an independent factor for predicting the progression of melanoma patients (HR = 0.64134, p = 0.00077)." (PMID 35837286, 2022). "In this part, we evaluated the prognostic value of upregulated LIPT1 in melanoma patients receiving immunotherapy." (PMID 35837286, 2022). "We next compared the protein levels of LIPT1 in melanoma and normal tissues downloaded from the Human Protein Atlas database and found that LIPT1 protein levels were dramatically upregulated in melanoma tissues as compared to normal tissues." (PMID 35837286, 2022). "The melanoma patients who expressed higher LIPT1 showed longer overall survival than those who expressed lower LIPT1." (PMID 35837286, 2022). "It has been found that LIPT1 is a favorable prognosis in patients with urothelial cancer or melanoma." (PMID 36195876, 2022). "Subsequently, the efficiency of LIPT1 for predicting the prognosis of melanoma patients receiving immunotherapy was evaluated through receiver operating characteristic (ROC) curve analysis." (PMID 35837286, 2022). "We confirmed the relationship between LIPT1 and PD-L1 expression in 470 melanoma patients using Spearman correlation analysis and validated a positive correlation between LIPT1 and PD-L1 expression (p = 0.001, Spearman = 0.15)." (PMID 35837286, 2022). "Subsequently, we evaluated the correlation between LIPT1 expression and immune cell infiltration in these melanoma patients." (PMID 35837286, 2022). "In our present study, we found that LIPT1 was upregulated in melanoma patients as compared to normal tissues when analyzing the data downloaded from TCGA and GTEx databases." (PMID 35837286, 2022).
melanoma (continued). "The melanoma patients with higher LIPT1 expression showed longer overall survival than those with lower LIPT1 expression after receiving immunotherapy, indicating the prognostic predictive value of LIPT1." (PMID 35837286, 2022). "The mRNA levels of LIPT1 were verified to be significantly higher in melanoma than in normal tissues in data downloaded from both GSE114445 and GSE100050." (PMID 35837286, 2022). "We divided the melanoma patients receiving immunotherapy downloaded from TCGA into two subgroups (LIPT1-high and LIPT1-low) according to the expression of LIPT1, and checked the survival status of these patients." (PMID 35837286, 2022). "In our present study, we found that LIPT1 was upregulated in melanoma by analyzing the data downloaded from the TCGA and GEO databases, respectively." (PMID 35837286, 2022). "To confirm the involvement of LIPT1 in melanoma, we divided the melanoma patients into two subgroups according to the expression of LIPT1, namely, the LIPT1-high group and the LIPT1-low group." (PMID 35837286, 2022). "Melanoma patients with high LIPT1 expression had longer overall survival than those with low LIPT1 expression after receiving immunotherapy, suggesting the predictive value of LIPT1 for prognosis." (PMID 36843949, 2023). "In melanoma, high expression of LIPT1 might be an indicator of the favorable prognosis of melanoma after immunotherapy." (PMID 38012558, 2023). "We downloaded and analyzed the expression of LIPT1 in sixteen melanoma and six normal tissues (GSE114445), and six melanoma and six normal tissues (GSE100050), respectively, to further confirm the differential expression of LIPT1 between melanoma and normal tissues." (PMID 35837286, 2022). "We, therefore, examined the role of LIPT1 in immunotherapy in melanoma patients." (PMID 35837286, 2022). "We, therefore, chose LIPT1 to further explore its role in the development of melanoma." (PMID 35837286, 2022). "Moreover, we checked the relationship between LIPT1 expression and overall survival in melanoma using the Cox analysis and the results were shown in the forest plots." (PMID 35837286, 2022). "The findings above indicated that high expression of LIPT1 might be an indicator of the favorable prognosis of melanoma after immunotherapy." (PMID 35837286, 2022). "In melanoma patients, Lv and colleague found that upregulated LIPT1 expression might suppress the infiltration of regulatory T cells (Tregs), thereby enhancing the immunotherapy efficacy." (PMID 36330439, 2022). "The prognostic value of upregulated LIPT1 in melanoma was further evaluated." (PMID 35837286, 2022). "LIPT1 could be a positive indicator for the prognosis of melanoma patients receiving immunotherapy." (PMID 35837286, 2022). "We further found that LIPT1 could be an indicator of the favorable prognosis of melanoma." (PMID 35837286, 2022). "It was found that in melanoma, upregulation of the CRG LIPT1 was positively correlated with PD-L1 expression and negatively correlated with Treg infiltration." (PMID 39482784, 2024). "We found that the expression of FDX1, LIAS, LIPT1, DLD, DLAT, MTF1, and CDKN2A were significantly lower in melanoma than in normal tissues." (PMID 36824136, 2023). "The combination of correlation analysis and prognosis analysis indicated that the expression of most cuproptosis-related genes was positively correlated with each other, and three genes (LIPT1, PDHA1, and SLC31A1) had a prognostic value in melanoma." (PMID 35837286, 2022). "In addition, previous studies revealed that high expression of LIAS and LIPT1 were favorable for the prognosis of clear cell renal cell carcinoma, and LIPT1 could also be considered as an indicator of favorable prognosis in melanoma." (PMID 36276092, 2022). "LIPT1 has been verified to strengthen the proliferating, invading, and migrating behaviors of LIHC cells, while LIPT1 is related to a favorable prognosis of individuals suffering from urothelial cancer or melanoma." (PMID 40367233, 2025).
melanoma (continued). "The univariate analysis indicated that LIPT1 expression (HR = 0.75235, p = 0.00389), age (HR = 1.02461, p < 0.0001) and TNM stage (HR = 1.37668, p < 0.0001) were correlated with overall survival of melanoma." (PMID 35837286, 2022). "Moreover, we detected that PD-L1 expression was positively correlated with some cuproptosis-related genes (CDKN2A, FDX1, LIPT1, and MTF1), but negatively correlated with other cuproptosis-related genes (ATP7B, DLST, and PDHA1) in an analysis of 470 melanoma patients." (PMID 35837286, 2022).
breast carcinoma (13 papers, 2022 to 2024). "It was shown that the expression of the following CRGs—CDKN2A, PDHA1, and lipoyltransferase 1 (LIPT1)—was associated with breast cancer incidence." (PMID 38732186, 2024). "The overexpression of LIPT-1 was associated with a favorable prognosis in patients with breast cancer, and it was also correlated with immune cell infiltration (B lymphocytes, fibroblasts, and CD8+ T lymphocytes)." (PMID 38732186, 2024). "Overexpression of LIPT1 is associated with favorable prognosis in tumor patients, such as breast cancer, clear cell renal cell carcinoma, ovarian cancer, and gastric cancer." (PMID 36330439, 2022). "And LIPT1 overexpression is associated with favorable prognosis in these patients, such as breast cancer, clear cell renal cell carcinoma, ovarian cancer and gastric cancer." (PMID 36330439, 2022). "Interestingly, LIPT1, a protein associated with copper-induced cytotoxicity, shows lower expression levels in breast cancer tissues compared to normal tissues." (PMID 39702350, 2024). "In the cohort study, high expression of LIAS, FDX1, LIPT1, DLD, PDH1, and ATP7B, coupled with low CDKN2A expression, was associated with favorable RFS in patients with estrogen receptor-positive early breast cancer (ER+ EBC)." (PMID 39867656, 2024). "A role for LIPT-1 as a novel prognostic and immunologic biomarker in breast cancer has been proposed." (PMID 38732186, 2024). "In our current study, we comprehensively analyzed the expression profile and stage characteristics of these CRGs in breast cancer, finding that CDKN2A, PDHA1 and LIPT1 expression were associated with pathological stage of BC." (PMID 36518756, 2022). "The results revealed that the expression of MTF1 (p = 0.037) and LIPT1 (p = 0.021) decreased as the pTNM stage increased in breast cancer." (PMID 36312586, 2022). "Correspondingly, in breast cancer, high expression of LIPT1 was related to good PFS (p = 1.9e-06), OS (p = 3.1e-06) and distant metastasis-free survival (DMFS) (p = 2e-07)." (PMID 36330439, 2022). "The IHC staining of LIPT1 was mainly weakly or negatively expressed in tumor tissue derived from kidney cancer, breast cancer and endometrial cancer." (PMID 36330439, 2022). "Given its distinct expression patterns in breast cancer, LIPT1 may serve as a potential biomarker for immunoassays and could provide valuable insights into the disease’s progression and treatment." (PMID 39702350, 2024). "Especially, the expression profiles and prognostic values indicated that LIPT1 might act as a tumor suppressor gene in breast cancer patients." (PMID 36330439, 2022). "In the GSE145548 cohort, the downregulation of ATF2 in MCF7 breast cancer cells resulted in substantial changes in the expression of cuproptosis regulators (DLST, GCSH, PDHA1, LIPT1, and DLD)." (PMID 39867656, 2024). "The univariate Cox regression demonstrated that LIPT1, PDHA1, and DLAT as predictor to poor survival and further classified breast cancer samples into three geneClusters (geneClusterA, geneClusterB and geneClusterC)." (PMID 37353799, 2023). "In the GSE145548 cohort, knockdown of ATF2 in breast cancer cells MCF7 resulted in the dramatic change of cuproptosis regulators (DLST, GCSH, PDHA1, LIPT1 and DLD)." (PMID 36733399, 2022). "In conclusion, multiomics approaches were conducted to develop a cuproptosis-related signature with six genes (DKN2A, MTF1, PDHA1, DLD, LIPT1, and FDX1) for breast cancer." (PMID 36312586, 2022). "Prognosis analysis revealed poor OS and RFS rates in breast cancer patients with elevated levels of CDKN2A and PDHA1 and low levels of MTF1, DLD, LIPT1, and FDX1." (PMID 36312586, 2022). "We then constructed a cuproptosis-related signature with six genes (DKN2A, MTF1, PDHA1, DLD, LIPT1, and FDX1) for breast cancer, which predicted the OS rate with an accuracy that ranged from medium to high." (PMID 36312586, 2022).
breast carcinoma (continued). "Multiomics approaches were used to create a cuproptosis-related signature with six genes (DKN2A, MTF1, PDHA1, DLD, LIPT1, and FDX1) for breast cancer." (PMID 36312586, 2022). "FDX1 (P < 1E‐12), LIAS (P = 2.22E‐16), LIPT1 (P < 1E‐12), DLD (P < 5.46E‐09), DLAT (P = 3.14E‐02), PDHA1 (P = 1.15E‐07), MTF1 (P = 1.07E‐09), and GLS (P = 2.48E‐05) were downregulated in breast cancer, while PDHB (P = 5.04E‐07) and CDKN2A (P = 1.62E‐12) were upregulated." (PMID 39432636, 2024). "Another vital discovery of our research was that we developed a cuproptosis-related prognostic signature containing six genes (CDKN2A, MTF1, PDHA1, DLD, LIPT1, and FDX1) for breast cancer, which predicted the OS rate with an accuracy that ranged from medium to high." (PMID 36312586, 2022). "Therefore, FDX1, LIPT1, and PDHB have favorable prognostic values before breast cancer recurrence." (PMID 39432636, 2024). "As cuproptosis-promoting genes, FDX1, LIAS, LIPT1, DLD, DLAT, and PDHA1 were under-expressed in breast cancer; at the same time, CDKN2A, which inhibited cuproptosis, was over-expressed in breast cancer, suggesting that cuproptosis might involve in the protective mechanism of BRCA." (PMID 39432636, 2024).
hepatocellular carcinoma (11 papers, 2022 to 2025). A malignant tumor that arises from hepatocytes. "Studies in hepatocellular carcinoma and acute myeloid leukemia (AML) suggest that LIPT1 expression is elevated and associated with poor prognosis, whereas another study in lung cancer found the opposite." (PMID 40073141, 2025). "LIPT1, a cuproptosis-related gene, was found to accelerate the growth and metastasis of hepatocellular carcinoma and is potentially a promising therapeutic target for hepatocellular carcinoma." (PMID 36672336, 2023). "LIPT1 plays an important role in hepatocellular carcinoma, which affects proliferation, invasion, and migration of this type of cancer." (PMID 36195876, 2022). "It turns out that LIPT1 is likely to be a very important potential target for the treatment of hepatocellular carcinoma." (PMID 36195876, 2022). "Our results suggest that LIPT1 can promote the proliferation, invasion and migration of hepatocellular carcinoma." (PMID 36195876, 2022). "Although LIPT1 can significantly affect the proliferation, invasion and metastasis of hepatocellular carcinoma, the specific mechanism is still unclear." (PMID 36195876, 2022). "Notably, heightened expression of LIPT1 in hepatocellular carcinoma cells has been observed to promote tumor cell proliferation, invasion, and migration, thus highlighting its potential as a viable therapeutic target." (PMID 38114959, 2023). "LIPT1 has been found to promote hepatocellular carcinoma proliferation, invasion, and migration." (PMID 37325063, 2023). "Cuproptosis-related LIPT1 may facilitate the proliferation and invasion of hepatocellular carcinoma cells, and may be a novel biomarker for hepatocellular carcinoma treatment." (PMID 38114959, 2023). "Finally, we determined that knockdown of LIPT1 gene expression inhibited proliferation and invasion of hepatoma cells." (PMID 36195876, 2022). "LIPT1 is likely to be a potential target for hepatocellular carcinoma therapy." (PMID 36195876, 2022). "Several studies have examined the effects of LIPT1 on the proliferation, invasion, and migration of HCC (hepatocellular carcinoma) cells." (PMID 38573998, 2024). "LIPT1 may be a very important target in the treatment of hepatocellular carcinoma." (PMID 36195876, 2022). "DLST SLC31A1, LIPT1, and UBE2D1 are reported to regulate cuproptosis in sepsis, hepatocellular carcinoma, multiple myeloma, thyroid carcinoma, oral squamous cell carcinoma, rheumatoid arthritis, periodontitis, gastric cancer, colorectal cancer, and myocardial infarction." (PMID 40980812, 2025).